LINC02349 (long independently transcribed non-coding RNA 2349)
Gene: Long non-coding RNA gene on chromosome 15 (61,713,005 to 61,731,389, forward strand). Ensembl gene ENSG00000259284.
Diseases named in the same sentence as LINC02349 in open-access papers:
LINC02349 is named in the same sentence as 1 disease in open-access papers, as found by Europe PMC text mining. Sharing a sentence is not in itself a finding about the gene and the disease. The quoted sentences say what the papers report.
osteoporosis (1 paper, 2020). A condition of reduced bone mass, with decreased cortical thickness and a decrease in the number and size of the trabeculae of cancellous bone (but normal chemical composition), resulting in increased fracture incidence. "Meanwhile, the data from GSE35958 shown that lower expression level of linc02349 in mesenchymal stromal cells (hMSC) from patients suffering from osteoporosis compared with hMSC from non‐osteoporotic donors." (PMID 32346990, 2020).